PRMT2 (protein arginine methyltransferase 2)
Diseases named in the same sentence as PRMT2 in open-access papers (continued):
Sharing a sentence is not in itself a finding about the gene and the disease.
cancer (21 papers, 2012 to 2025). A tumor composed of atypical neoplastic, often pleomorphic cells that invade other tissues. "Conversely, the PRMT2 protein is implicated in cancer metabolism through the modulation of hormonal receptor signaling, gene expression, and cell cycle regulation." (PMID 39982908, 2025). "To assess the clinical relevance of our findings, we showed the physical interaction of HIF1α and PRMT2 in cancer-associated adipocytes of human luminal-type BC specimens obtained commercially." (PMID 35593921, 2022). "Additionally, as a transcriptional coactivator of genes involved in oncogenesis, PRMT2 has been implicated in cancer pathogenesis and is, therefore, a potential target for cancer therapy." (PMID 34833139, 2021). "For instance, PRMT2 and its splice variants were found to play a role in the progression of breast cancer by modulation of promoter activities of the ERα-targeted genes thereby controlling cancer cell proliferation." (PMID 23202904, 2012). "This indicates that PRMT2 is a key nexus between the intrinsic functions of cancer cells and the signaling network of the microenvironment." (PMID 41154773, 2025). "The type I PRMT family includes PRMT1, PRMT2, PRMT3, PRMT4, PRMT6, and PRMT8, which have been linked to various aspects of cancer development, including carcinogenesis, metastasis, and drug resistance." (PMID 39699269, 2025). "Nevertheless, recent studies show promise in mediating cancer progression through the inhibition of PRMT2." (PMID 40869229, 2025). "PRMT2 exhibits strikingly divergent functions across different cancer types and even within different models of the same cancer." (PMID 41154773, 2025). "In cancer, PRMT2 expression is upregulated in hepatocellular carcinoma and glioblastoma, and is involved in tumor development." (PMID 38902349, 2024). "In GSE14520, the expressions of PRMT1, PRMT3, PRMT4, and PRMT5 were upregulated in cancer tissues, whereas PRMT2 and PRMT8 were downregulated." (PMID 37627211, 2023). "As a member of the protein arginine methyltransferase (PRMT) family, PRMT2 had been demonstrated to catalyze the arginine methylation of target proteins and link them to the development and progression of cancers." (PMID 36715873, 2023). "Herein, we showed that PRMT2 facilitates RCC cancer progression by regulating H3R8me2a modification on the WNT5A promoter." (PMID 37173306, 2023). "Since RORα and RORγ are dysregulated in multiple cancer types based on published articles, they likely participate in carcinogenesis through modulating molecules such as IL-17, PRMT2, and AR or as receptors for sterols, such as vitamin D3 derivatives." (PMID 29904382, 2018). "PRMT2 is a novel target for new therapeutic therapies in cancer treatment." (PMID 40869229, 2025). "However, various studies have since demonstrated the implication of PRMT2 in transcriptional regulation independently of its catalytic activity and, therefore, in cancer." (PMID 34833139, 2021). "Similarly, the gene PRMT2, a gene that is involved in cancer invasion, growth, and presumably EMT, and whose splice variants have been linked to cancer, contains an exon that is overexpressed near the stromal and normal archetypes, as well as some of the epithelial-like tumors." (PMID 38674106, 2024). "In cancer tissues of GSE25097, the expressions of PRMT2, PRMT3, PRMT4, PRMT5, and PRMT7 were upregulated in cancer tissues, whereas the expressions of PRMT6 and PRMT9 were downregulated." (PMID 37627211, 2023). "In GSE36376, the expressions of PRMT1, PRMT2, PRMT3, PRMT4, PRMT5, and PRMT7 were upregulated in cancer tissues." (PMID 37627211, 2023). "There is no direct evidence for dysregulation of other PRMTs, such as PRMT2, PRMT4 and PRMT5 in lung tumorigenesis, although these molecules participate in the pathogenesis of other types of human cancer." (PMID 23202904, 2012).
cancer (continued). "Given that PRMT2 is a significant arginine methylase involved in cancer progression, we investigated the hypothesis that PADI4 may directly citrullinate PRMT2." (PMID 40078091, 2025). "While PRMT2 does regulate cell growth, silencing of the protein does not bring cancer cells to apoptosis." (PMID 40869229, 2025). "To explore the relationship between PRMT2/4-mediated BRD4 methylation and DDR, we induced DNA damage using a topoisomerase II inhibitor, etoposide, which has been used in PRMT1/5-relevant studies and is widely used for cancer treatment." (PMID 36475791, 2022). "Unlike other PRMTs, PRMT2 has been rather shown to prevent cancer cell proliferation." (PMID 32121248, 2020). "Also considering that PRMT2 may directly participate in multiple cellular pathways in cancers, it will be interesting to further identify potential non-histone substrates in relevant models." (PMID 30382083, 2018). "However, an earlier study suggested that high expression of RORγ1, but not RORγt, by cancer cells was related to a high distance metastasis-free survival and was inversely correlated with decreased expression of PRMT2, which could suppress cell migration in BC." (PMID 29904382, 2018).
infection (2 papers, 2016 to 2023). The state of being infected such as from the introduction of a foreign agent such as serum, vaccine, antigenic substance or organism. "Moreover, PRMT2 ablation promotes productive infection and decelerates the latency re-entry of the reactivated provirus." (PMID 37949879, 2023). "Despite the comparable infection rates in both control and PRMT2-depleted cells, flow cytometry results demonstrated that PRMT2 depletion leads to a prominent increase in actively infected cells and a concomitant reduction in the proportion of latently infected cells." (PMID 37949879, 2023).
PRMT2 also shares sentences with these, for which no sentence is quoted: hepatocellular carcinoma (5 papers); Intellectual disability (2); acute coronary syndrome (1); acute leukemia (1); cardiovascular diseases (1); Crohn disease (1); heart failure (1); HIV-1 infection (1); retinoblastoma (1); Type 2 diabetes (1); ulcerative colitis (1).